SPATA31D1 (SPATA31 subfamily D member 1)
Description:
May play a role in spermatogenesis.
Synonyms: FAM75D1; FLJ46321
Tractability: Antibody: UniProt predicts a signal peptide or a membrane-spanning region.
Gene: Protein-coding gene on chromosome 9 (81,988,772 to 81,995,253, forward strand). Ensembl gene ENSG00000214929.
Subcellular location: Membrane
Gene Ontology:
Cellular component: membrane
Genetic constraint (gnomAD): Loss-of-function variants: 6 observed, 13.5 expected, observed/expected ratio (o/e) 0.44, 90% interval 0.24 to 0.88. The synonymous counts are far from expectation, so gnomAD's model fits this gene poorly and the ratio says little. Missense variants: 2,445 observed, 1,937.7 expected, observed/expected ratio (o/e) 1.26, 90% interval 1.22 to 1.3. Synonymous variants: 903 observed, 741.44 expected, observed/expected ratio (o/e) 1.22, 90% interval 1.15 to 1.29.
Homologues: Orthologues: chimpanzee SPATA31D1 (54% identical), mouse Spata31f3 (4% identical). Paralogues in human: SPATA31D4 (53% identical), SPATA31D3 (53% identical), SPATA31A6 (23% identical), SPATA31A3 (23% identical), SPATA31A1 (23% identical), SPATA31A5 (23% identical), SPATA31A7 (23% identical), SPATA31E1 (22% identical), SPATA31C1 (20% identical), SPATA31C2 (19% identical), SPATA31F1 (16% identical), SPATA31F3 (3% identical).
Diseases named in the same sentence as SPATA31D1 in open-access papers:
SPATA31D1 is named in the same sentence as 3 diseases in open-access papers, as found by Europe PMC text mining. Sharing a sentence is not in itself a finding about the gene and the disease. The quoted sentences say what the papers report.
depression (1 paper, 2020). "Three replicated loci were previously reported (ITIH3, FHIT, BAG5), but the other seven (ZNF804A, MIR3143, PSORS1C2, STK19, SPATA31D1, RTN1, TCF4) were novel for depression." (PMID 30626913, 2020).
SPATA31D1 also shares sentences with these, for which no sentence is quoted: cancer (1 paper); schizophrenia (1).